SLC2A1 (solute carrier family 2 member 1)
Diseases named in the same sentence as SLC2A1 in open-access papers (continued):
Sharing a sentence is not in itself a finding about the gene and the disease.
tumor (continued). "Among the hub genes, SLC2A1, CDH3 and EFHD2 increased across tumour stages and were associated with poorer survival probability, suggesting their critical roles in iCCA." (PMID 34013637, 2021). "So, when SLC2A1 is abnormally activated in the plasma membrane of tumor cells, it can transport large amounts of glucose from the extracellular to the mitochondria, thus providing energy to the cancer cells." (PMID 34906142, 2021). "Tumor cells must upregulate the expression of the glucose transporters SLC2A1 (GLUT1) and SLC5A1 (SGTL1) to increase glucose uptake." (PMID 33783998, 2021). "Multiple cancer-related pathways up-regulate SLC2A1 in tumor cells, including HIF1, MYC, PI3K-Akt, and RAS-MAPK." (PMID 33810575, 2021). "TRPS1 and SLC2A1 have previously been implicated in PC and AR action, and decreased EFS expression has been associated with more advanced PC and tumor recurrence." (PMID 33974560, 2021). "Analysis by RT-qPCR and western blotting showed that the expression levels of SLC2A1 were significantly decreased in tumor tissues after circHECTD1 knockdown." (PMID 34079759, 2021). "After coculture of autophagic CAFs with T24 cells, cell proliferation and invasion were both enhanced, along with increased expression of MCT1, MCT4, HK2, and SLC2A1, as well as elevated levels of lactate in the tumor microenvironment." (PMID 34122670, 2021). "SLC2A1 can enhance intracellular glucose as an energy source and thereby provide favorable conditions for tumor growth and subsequent dissemination and metastasis." (PMID 33735188, 2021). "Taken together, miR-30d plays a tumor-suppressive role in resisting pancreatic tumorigenesis via a selective target loss of HK1 and SLC2A1-regulator RUNX1, subsequently resulting in inhibition of the Warburg effect." (PMID 34021267, 2021). "SLC2A1, also known as glucose transporter type 1 (GLUT1), is well characterized in cancer and is associated with tumor progression and metastasis, including in LUAD where is has previously been shown to be upregulated and associated with poorer prognosis." (PMID 34977043, 2021). "Reportage of tumor HiF status was calculated from the averaged, normalized levels of hypoxia response genes: Glut1 (SLC2A1), Glut3 (SLC2A3), ADM, VLDLR, and VEGFA." (PMID 34681642, 2021). "Compared to that in normal mucosa, SLC2A1 expression was significantly higher in primary cancers (189 normal mucosa versus 189 primary tumor samples, p < 0.001)." (PMID 33735188, 2021). "Analysis showed that MMP3 and SLC2A1 expression were significantly higher in OSA tissue compared to non-tumor tissue and protein expression in OSA was confirmed by immunohistochemistry." (PMID 34414229, 2021). "Since tumor cells have an increased metabolic rate, the expression of SLC2A1 is often deregulated in different cancer types and since they are involved in the support of tumor cells with energy, they present therapeutic targets." (PMID 32599841, 2020). "In the current study, SLC2A1 expression was significantly higher in OSA tissue compared to non-tumor tissue." (PMID 32854182, 2020). "Among the four selected genes, ENO1, GAPDH, and SLC2A1 were significantly upregulated in tumor tissues compared with normal tissues." (PMID 32084009, 2020). "A previous study indicated that the up-regulation of SLC2A1 accelerated tumor cell proliferation and metastasis." (PMID 31311829, 2019). "The CA9 mRNA level was also correlated with the mRNA expression of other HIF1 target genes in the investigated tumor samples such as glucose transporter 1 (Glut1≙ SLC2A1), glyceraldehyde-3-phosphate dehydrogenase (GAPDH), VEGFa and with miRNA-210 expression." (PMID 30654595, 2019). "Current PET-CT technologies use 18F-deoxyglucose as a tracer for cancer imaging, based on the tumor-specific upregulation of glucose transporter-1 (GLUT-1; also known as SLC2A1) on tumor cells." (PMID 29562706, 2018). "Cre-mediated Slc2a1 excision completely prevented tumor formation when cells were grown as orthotopic xenografts." (PMID 27998284, 2016).
tumor (continued). "The positive correlation between the same hypoxia gene signature and HIF-1α, VEGFA and SLC2A1 suggests that the imaging parameters reveal real functional aspects reflecting the oxygen status in the tumor." (PMID 27634881, 2016). "We found gene expression value of VEGFA and SLC2A1 in the tumor component to be significantly positively correlated to stromal HIF-1α." (PMID 27634881, 2016). "Our previous study showed that shRNA knockdown or Cre-mediated excision of Slc2a1 from cells that had previously grown as tumors in vivo only resulted in a partial inhibition of tumor growth." (PMID 27998284, 2016). "To validate the up-regulation of SLC2A1 at the transcriptional level in GC, we further compared SLC2A1 expression patterns in 20 GC tumor tissues to their normal counterparts using real-time PCR." (PMID 26193257, 2015). "The mice injected with the SLC2A1-expressing MGC-803 cells demonstrated a significantly larger in tumor size than those injected with the vector-expressing MGC-803 cells (p < 0.001)." (PMID 26193257, 2015). "Western blot analysis performed on the expression profiles of the MTOR signal cascade in the tumor adjacent tissues revealed that the treated group expressed a lower level of MTOR/EIF4EBP1/YY1/MYC/SLC2A1 signaling than the untreated group." (PMID 25909713, 2015). "More specifically, SLC2A1 is upregulated in cancers to accelerate the uptake of glucose and meet the energy needs of the tumor for an accelerated rate of glycolysis." (PMID 25830305, 2015). "The mice injected with the SLC2A1-expressing MGC-803 cells also demonstrated a significant increase in tumor weight than those injected with the vector-expressing MGC-803 cells (p < 0.001)." (PMID 26193257, 2015). "Solute carrier family 2 (facilitated glucose transporter) member 1 protein SLC2A1, also known as glucose transporter type 1 (GLUT1), has been associated with tumor progression, metastasis, and poor prognosis in many human solid tumors." (PMID 26193257, 2015). "Our data revealed that the mean expression level for SLC2A1 in GC tumor tissues was roughly 3-fold higher than that in the normal gastric mucosa (p < 0.001)." (PMID 26193257, 2015). "SLC2A1 was found to have a positive relationship with grade, tumor front grading (TFG) score, and depth and mode of invasion (p < 0.05)." (PMID 25412955, 2015). "In 57.8% (115/199) of the GC tumors, a predominantly cytoplasmatic staining with strong positive tumor cells for SLC2A1 was detected, whereas 12.5% (1/8) normal gastric specimens showed only weak irregular cytoplasmatic staining." (PMID 26193257, 2015). "The observed SLC2A1 overexpression induced by DERL3 epigenetic loss generates a Warburg effect in the studied cells and it highlights a group of human tumours that are more sensitive to drugs targeting glycolysis." (PMID 24699711, 2014). "Reportedly, glucose and amino acids are increased in tumor cells to meet the increased demand for robust proliferation, for example, by the induction of SLC2A1 and SLC5A1 for glucose, and by the induction of SLC7A5 for amino acids." (PMID 24718268, 2014). "Most importantly, SLC2A1 overexpression mediated by DERL3 epigenetic loss contributes to the Warburg effect in the studied cells and pinpoints a subset of human tumours with greater vulnerability to drugs targeting glycolysis." (PMID 24699711, 2014). "Furthermore, we identify SLC2A1 as a clinically relevant therapeutic target, offering new insights into tumor VI." (PMID 42274609, 2026). "Importantly, administration of the SLC2A1 inhibitor BAY-876 effectively suppressed tumor progression and intrahepatic metastasis in the orthotopic ICC mouse model." (PMID 42274609, 2026). "This indicates that SLC2A1 not only plays a role in tumor cell growth and metastasis but may also influence the tumor microenvironment and its interaction with the immune system." (PMID 39992528, 2025).
tumor (continued). "In addition, knockdown of RP11-544M22.13 significantly reduced the levels of ki67 in tumor cells, which was rescued by overexpression of SLC2A1." (PMID 41309566, 2025). "SLC2A1 was significantly upregulated in 22 out of 33 tumor tissues, covering diverse cancer types." (PMID 40746529, 2025). "Moreover, significantly upregulated SLC2A1/5/6/8/14 expression levels were observed in most tumor types among the SLC2A family members." (PMID 40824962, 2025). "SLC2A1 affects tumor immune escape via inhibitory interactions with regulatory T cells." (PMID 41419193, 2025). "This suggests that SLC2A1 may play a crucial role in various tumor cell types or cellular states, particularly concerning tumor aggressiveness and metastatic potential." (PMID 39992528, 2025). "This indicates that SLC2A1 is not only a regulator of tumor cell metabolism but may also directly promote cancer progression by participating in cellular migration and invasion." (PMID 39992528, 2025). "Additionally, ATG4B closely interacts with SLC2A1, promoting the Warburg effect in tumor and increasing L-lactate production and glucose uptake." (PMID 41019083, 2025). "In addition, overexpression of RP11-544M22.13 significantly increased the level of KI-67 in tumor cells, while knockdown of SLC2A1 rescued this level." (PMID 41309566, 2025). "Second, tumor subsets enriched for microenvironment features, including hypoxia markers (e.g., Slc2a1, Pdk1, Car9), extracellular matrix (ECM) genes (e.g., Matn2, Fn1, Dcn, Col6a1), vasculature (e.g., Cdh5, Pecam1, Vwf), and interferon response genes (e.g., Rsad2, Ifit3, Gbp3, Cxcl10, Cd274)." (PMID 40171265, 2025). "Moreover, stimulation with mouse-derived recombinant SPP1 protein induced the expression of pro-tumor genes (such as Arg1, Slc2a1, and Nos2) in MDSCs while repressing the expression of anti-tumor genes (such as Il1b, Tnfa, and Il12b)." (PMID 39066845, 2024). "Besides, although this research provided initial validation of SLC2A1’s role in LUAD, genes express their effects through multiple mechanisms, including transcriptional regulation, epigenetics, tumor microenvironment, and mutation patterns." (PMID 39669580, 2024). "Other novel genes up-regulated in tumor cells, like SLC2A1 and REG4, promote M2 polarization." (PMID 39256888, 2024). "Notably, SLC7A11 and SLC2A1 were identified as key genes for disulfide metabolism disorders in tumor cells and exhibited a high predictive value for OS." (PMID 38831301, 2024). "Both glucose uptake and the expression of the glucose transporter Glut1 (Slc2a1), but not that of Glut2 (Slc2a2), Glut3 (Slc2a3), or Glut4 (Slc2a4), were elevated in Cpt1a-deficient ErbB2 tumor cells." (PMID 39097623, 2024). "Moreover, SLC2A1 has been shown to be a key gene in tumor glucose metabolism, which promotes glycolysis in cancer cells and thus affects the growth and metastasis of cancer cells." (PMID 38517922, 2024). "CEACAM6 and SLC2A1 may also play a role in IPMN tumor progression, with increased expression of these genes in high‐grade versus low‐ and intermediate‐grade IPMNs being previously observed." (PMID 39660530, 2024). "SLC2A1 is overexpressed in various tumors, which could promote tumor glycolysis, proliferation, and migration." (PMID 39256888, 2024). "While providing energy for tumors, SLC2A1 promotes tumor growth and metastasis." (PMID 39275122, 2024). "Herein, we further investigated the association between glycolysis and IDO1 in PC with bioinformatic analysis and found the expression of SLC2A1, SLC2A3, SLC2A5 (encoding GLUT1, GLUT3, GLUT5 protein), and IDO1 in the tumor tissues of PC patients was increased compared to the adjacent normal tissues." (PMID 38706741, 2024).
tumor (continued). "In vitro cell experiments have shown that interfering with DARS2 expression can inhibit the proliferation and migration of LUAD cells, promote cell apoptosis, and inhibit the glycolytic activity of tumor cells by inhibiting the expression of glycolytic related genes SLC2A1, GPI, ALDOA, and PGAM1." (PMID 37626419, 2023). "Real-time qPCR analysis of glucose transporter and glycolytic genes in the xenograft tumor tissues showed that ACE2 overexpression suppressed the mRNA levels of SLC2A1, HK2, ENO1, PFKL, LDHA, and PDK1, while inhibition of Mas receptor with A779 restored the expression of glycolytic components." (PMID 37215979, 2023). "Furthermore, METTL3 is involved in stabilizing the mRNA of HK2 and SLC2A1 (GLUT1), and degrading the mRNA of APC; all these effects are associated with the glycolysis and proliferation of tumor cells." (PMID 37965577, 2023). "We found that stem cell-like GBM tumor subpopulations possessed higher basal levels of glycolytic activity and increased expression of several glycolysis-related enzymes including, GLUT1/SLC2A1, PFKP, ALDOA, GAPDH, ENO1, PKM2, and LDH, compared to their non-stem-like counterparts." (PMID 37420311, 2023). "Additionally, the expressions of ECT2, FGD6, MMP14, and SLC2A1 were related to the staging of the tumor." (PMID 37604837, 2023). "SLC2A1 was highly expressed in HCC tumor tissue and correlated with clinical stage and prognosis." (PMID 37443106, 2023). "Notably, SLC2A1, SLC25A29, and SLC27A4 were identified as key genes associated with survival and tumor stage." (PMID 37775731, 2023). "Immunohistochemical staining of IPMN nodules, a high-risk feature, and an indication for surgical resection, also revealed significantly increased expression of SLC2A1/GLUT1 glucose transporter in samples consistent with advanced neoplasia when compared to low-grade dysplasia." (PMID 36980608, 2023). "The downregulation of MIR-150 may promote FL transformation by enhancing glucose metabolism through the upregulation of SLC2A1/GLUT1 in FL tumor cells." (PMID 37182123, 2023). "In the other three cancers, although there are no relevant studies yet, this result is revealing and suggests that we may be able to explore the factors affecting tumor immune response from the perspective of SLC2A1 promoter methylation." (PMID 36712872, 2022). "Therefore, we assessed the relevance of SLC2A1 to tumor biological function at the single-cell level using the CancerSEA database." (PMID 36712872, 2022). "SLC2A1 not only enhanced cancer glycolysis, but also affected the tumor microenvironment." (PMID 36358765, 2022). "We explored the differences in SLC2A1 phosphorylation in tumor and normal tissues." (PMID 36712872, 2022). "Therefore, we explored the potential correlation between SLC2A1 expression and tumor-infiltrating immune cells by performing comprehensive research." (PMID 36712872, 2022). "We pointed out that the high expression of SLC2A1 may enhance an anti-tumor immune response, stating that SLC2A1 plays a critical role in the immune regulation of CRC." (PMID 35399515, 2022). "The expression of SLC2A1 has been proved to be related to the hypoxia level of tumor." (PMID 35517408, 2022). "SLC2A1 is a transporter that mainly mediates the regulation of tumor energy metabolism." (PMID 35517408, 2022). "In addition, the expression level of SLC2A1 has a certain correlation with sample type, tumor stage, venous invasion, and lymphatic invasion." (PMID 36065306, 2022). "These analyses point out that SLC2A1 maybe participated in the immune respond to CRC tumor microenvironment, particularly to B cell, neutrophil, and DC." (PMID 35399515, 2022). "Additionally, lower levels of SLC2A3, SLC2A6, SLC2A9, SLC2A12, and SLC2A14 and higher levels of SLC2A1, SLC2A5, SLC2A10, and SLC2A11 had an association with advanced tumor stage." (PMID 36518662, 2022).
tumor (continued). "A previous study suggested that the upregulated expression level of SLC2A1 may increase the tumor cell proliferation and metastasis." (PMID 35664334, 2022). "To explore the clinical significance and prognostic value of SLC2A1, we used massive databases to explore in depth the methylation of SLC2A1, and we investigated the differences in immune infiltration between tumor and normal tissues using the gene expression omnibus (GEO) dataset." (PMID 36065306, 2022). "SLC2A1 plays an important role in both normal human metabolism and tumor cell glycolysis." (PMID 35399515, 2022). "SLC2A1 expression is associated with various immune infiltration cells and may influence CRC tumor immune microenvironment by promoting neutrophil infiltration." (PMID 35399515, 2022). "SLC2A1 was found to be upregulated and play a role in tumor progression in various cancers." (PMID 36733386, 2022). "ROC curve indicated that SLC2A1 had high predictive accuracy for the outcomes of tumor." (PMID 35399515, 2022). "Tumor-associated myeloid cells exhibited higher transcriptional expression of molecules linked to the “find me” (G2A), “eat me” (CD93, TIM1, SCARF1, SLC2A1, GAS6, TREM2, AXL, C1QA), and downstream processing (NR1H3, ATG7, PPARG, ABCA1, PPARD, DOCK180) phases of efferocytosis." (PMID 36439171, 2022). "Among the many elements related to glucose metabolism, solute carrier family 2 member 1 (SLC2A1), a glucose transporter-encoding gene that controls glucose uptake, could play a pivotal role in the growth and proliferation of tumor cells." (PMID 33735188, 2021). "Within the unfavorable organic anion transporters, SLC2A1 is present in five tumor entities." (PMID 32599841, 2020). "Interestingly, enhancement of glucose transport mediated by Slc2a1 supports glycolytic metabolism in ECs of tumor vessels." (PMID 33138917, 2020). "While SLC2A1 overexpression rescued the anti-tumor effect of miR-152-3p on U251 cells (P < 0.001)." (PMID 31492194, 2019). "LINC00174 promoted glycolysis and tumor progression by targeting miR-152-3p/SLC2A1 axes." (PMID 31492194, 2019). "Moreover, knockdown of SLC2A1 by siRNA or specific inhibitors, which blocked glucose uptake by tumor cells, cannot further reduce the ability of glycolysis." (PMID 28440026, 2017). "Similarly, the mice injected with the SLC2A1-expressing MKN28 cells demonstrated a significant larger in tumor size and tumor weight than those injected with the vector-expressing MKN28 cells (p < 0.01)." (PMID 26193257, 2015). "This was further emphasized by mRNA analysis of whole tumor preparations, where a significant elevation in hypoxia-related genes (i.e. Glut-1 (Slc2a1), Angpt2, Stc2, and Semaphorin B) could be seen coinciding with reduced CD31-staining." (PMID 26673090, 2015). "Up-regulated SLC2A1 expression contributes to carcinogenesis and tumor progression." (PMID 26193257, 2015). "Meanwhile, elevated SLC2A1 also contributes to tumor metastasis in vitro." (PMID 26193257, 2015). "We observed that the expression levels of the phosphorylated active form of MTOR (pMTOR) and YY1 were significantly elevated at as early as one month of age and persistently activated throughout the study period, while MYC and SLC2A1 expression was found upregulated only upon tumor formation." (PMID 25909713, 2015). "Additionally, over-expression of SLC2A1 in GC cells promotes cellular proliferation and metastasis in vitro and enhances tumor growth in vivo as well as enhancement of glucose utilization." (PMID 26193257, 2015). "Notably, after oncogene K-Ras activation, BASCs show upregulation of the glucose transporter (Glut1/Slc2a1), considered as an important player of the active control of tumor cell metabolism by oncogenic K-Ras." (PMID 25144301, 2014). "Finally, we found that SLC2A1 exerted an important role in the tumour suppressor effects mediated by DERL3." (PMID 24699711, 2014).